STAT1 (signal transducer and activator of transcription 1)
Diseases named in the same sentence as STAT1 in open-access papers (continued):
Sharing a sentence is not in itself a finding about the gene and the disease.
germ cell tumour (1 paper, 2007). "Previous studies have established that testicular germ cell tumour cells can express both mRNA and protein of IFN-γ and the expressed IFN-γ is able to induce the chemokine IP-10, indicating its biological activity, whereas it is not able to phosphorylate the downstream STAT1." (PMID 17622250, 2007).
giant cell tumor (1 paper, 2018). A benign, intermediate, or malignant tumor that arises from the bone or soft tissue. "In this study, the aim is to verify, by immunohistochemistry, the expression of IGF1, MDM2, STAT1, and RAC1 and investigate their potential relationship with GCT recurrence, in a large cohort of patients with a giant cell tumor of the bone." (PMID 29651441, 2018).
giant cell tumor of bone (1 paper, 2018). "In our previous study, mouse double minute 2 homolog (MDM2), insulin-like growth factor 1 (IGF1), signal transducer and activator of transcription 1 (STAT1), and Rac family small GTPase 1 (RAC1) were correlated with the recurrence of giant cell tumor of bone (GCT)." (PMID 29651441, 2018).
gram-negative bacterial infections (1 paper, 2017). Infections caused by bacteria that show up as pink (negative) when treated by the gram-staining method. "Some studies have reported that STAT1 might play a critical role in innate immunity against Gram-negative bacterial infection, especially for inducible nitric oxide synthase (iNOS) expression." (PMID 29311915, 2017).
gynecological cancers (1 paper, 2025).
H1N1 virus infection (1 paper, 2011). "This is indicative of suppression of STAT1 at later stages of pandemic H1N1 virus infection, which might decrease the overall host innate immune response." (PMID 21439068, 2011).
hemorrhagic disease (1 paper, 2020). Spontaneous or near spontaneous bleeding caused by a defect in clotting mechanisms (blood coagulation disorders) or another abnormality causing a structural flaw in the blood vessels (hemostatic disorders). "Notably, no overt bleeding was observed in the organs of LCMV-infected STAT1 KO mice, contrary to the reports of hemorrhagic diseases in systemic LCMV infection." (PMID 32310998, 2020). "To investigate whether hemorrhagic disease contributes to lethality in LCMV-infected STAT1 KO, we determined the quantitative changes in the leukocyte subsets, platelets, red blood cells (RBCs), % hematocrit and hemoglobin level in the peripheral blood of these mice." (PMID 32310998, 2020).
Hepatic steatosis (1 paper, 2021). Steatosis is a term used to denote lipid accumulation within hepatocytes. "What's more, loss of STAT5 signaling led to hepatic steatosis through elevated STAT1/STAT3 activity, which was also observed in STAT5A over‐/downexpression cells." (PMID 33155364, 2021). "Notably, loss of STAT5 signaling results in hepatic steatosis through elevated STAT1/STAT3 activity and CD36." (PMID 33155364, 2021).
hereditary thrombocytosis (1 paper, 2013). "In line with our finding, JAK2 germline mutations with a kinase activity lower than JAK2V617F and a specific activation of STAT1 were identified in hereditary thrombocytosis." (PMID 24066127, 2013).
HTLV-2 infection (1 paper, 2013). "IFN-γ-related priming for STAT1 activation may be an alarming signal that biases the immune response toward a Th1-model of containment of HTLV-2 infection, overcome by a peculiar STAT5Δ activation in HIV-1-infected individuals." (PMID 24391628, 2013). "The observation that PBMCs obtained from both HIV-1- and HTLV-2-infected individuals activate STAT1 as a consequence of the spontaneous release of IFN-γ is supported by previous findings indicating an up-regulation of this cytokine following either HIV-1 or HTLV-2 infection." (PMID 24391628, 2013).
Hutchinson-Gilford progeria syndrome (1 paper, 2023). "Notably, premature aging in the Hutchinson-Gilford progeria syndrome (HGPS) is associated to a potent STAT1-mediated IFN response that appears to be involved in cellular decline." (PMID 37045990, 2023).
hyperphosphatemia (1 paper, 2023). Abnormally high level of phosphate in the blood. "Overall, our data indicate that the JAK-STAT pathway, more specifically the activation of JAK1-JAK2 and STAT1, acts as a brake in the osteogenic trans-differentiation of VSMCs induced by hyperphosphatemia." (PMID 38254629, 2023). "Herein, we show that hyperphosphatemia induces the phosphorylation of JAK1 and JAK3 and of the downstream effector STAT1 in HASMCs." (PMID 38254629, 2023).
hypophosphatemia (1 paper, 2011). Lower than normal levels of phosphates in the circulating blood.
idiopathic inflammatory myopathies (1 paper, 2022). "Previous research reported that PSMB8, PSMB9 and PSMB10 expressed at significantly abundant levels in dendritic cells, monocytes, and CD8+ T-cells in idiopathic inflammatory myopathies, which correlated highest with STAT1, IRF1 and IFN-γ expression." (PMID 35933405, 2022).
immune thrombocytopenia (1 paper, 2025). "ADAP restrains Fcγ receptor I/IV transcription and mediates the phagocytic ability of splenic macrophages by interacting with STAT1 in immune thrombocytopenia." (PMID 39903516, 2025).
immunotoxicity (1 paper, 2022). "Preliminary results indicate indeed a reduced expression of STAT1 following G exposure, which could be reversed by ICI (data not shown), indicating STAT1 as a relevant target to explain G immunotoxicity." (PMID 35359959, 2022).
infantile hemangioma (1 paper, 2018). "The phosphorylated/activated forms of STAT1, STAT3 and STAT5 are present in the endothelium and cells in the interstitium of proliferating infantile hemangioma." (PMID 29725593, 2018). "The phosphorylated/activated forms of STAT1, STAT3 and STAT5 are reduced or absent in involuted infantile hemangioma." (PMID 29725593, 2018).
Intellectual disability (1 paper, 2025). "In this regard, it would be of interest to examine whether intellectual disability and the growth retardation phenotype associated with Cys1790Arg and perhaps other CBP TAZ2 variants may involve increased transcriptional activity of STAT1." (PMID 40860344, 2025).
intracerebral hemorrhage (1 paper, 2021). A cerebrovascular disorder characterized by bleeding into one or both cerebral hemispheres including the basal ganglia and the cerebral cortex. "However, after intracerebral hemorrhage, increased expression of integrin β1 in the brain significantly improved neurobehavioural score with decrease of neutrophil infiltration through JAK2/STAT1 pathway." (PMID 33564320, 2021).
intrahepatic cholangiocarcinoma (1 paper, 2024). A carcinoma that arises from the intrahepatic bile duct epithelium in any site of the intrahepatic biliary tree. "HP1α was upregulated in intrahepatic cholangiocarcinoma (ICCA) tissues and regulated the proliferation of ICCA cells by inhibiting the interferon pathway in a Signal Transducer and Activator of Transcription 1 (STAT1)-dependent manner." (PMID 38812060, 2024).
ischemic cardiomyopathy (1 paper, 2020). Ischemic cardiomyopathy is a cardiomyopathy in which a weakness in the muscle of the heart due to inadequate oxygen delivery to the myocardium with coronary artery disease being the most common cause. "Interestingly, Stat1 and Stat3 have been suggested to play antagonistic roles, where Stat1 worsens, while Stat3 protects the heart from ischemic cardiomyopathy by either activating or inhibiting inflammation, respectively." (PMID 33037313, 2020).
kidney infection (1 paper, 2020). "We compared A2 and A2.V296F kidney infection in CD8+ T cell-depleted Stat1–/– mice by staining kidney sections at day 7 pi for VP1." (PMID 32940605, 2020).
leiomyoma (1 paper, 2007). A well-circumscribed benign smooth muscle neoplasm characterized by the presence of spindle cells with cigar-shaped nuclei, interlacing fascicles, and a whorled pattern. "They included several genes such as NR2F1, PNN, Smad4, Smad5, STAT5B, JUN, TGIF2, and ATF1 that were over-expressed while RUNX3, STAT1, STAT6, EGR3, GAS7, Smad1, and EDF1 were underexpressed in leiomyomas as compared to keloid/incisional scars." (PMID 17718906, 2007).
leukocytosis (1 paper, 2016). "There is one case with persistent leukocytosis and hypereosinophilia in a 2 month of age child who later was diagnosed as STAT1 deficiency." (PMID 27222657, 2016).
liver failure (1 paper, 2020). A liver disease characterized by the liver losing or has lost all of its function. "Together, this demonstrates the onset of liver failure due to infection with CCHFV and mimics the findings observed in humans and in the IFNAR−/− and STAT1−/− mouse models." (PMID 32704046, 2020).
lumbar disc herniation (1 paper, 2023). "Immunohistochemical staining of PSMB9, STAT1, and TAP1 was performed in 5 patients with spinal tuberculosis and 5 patients with lumbar disc herniation." (PMID 37340462, 2023).
lymphocytic leukaemia (1 paper, 2012). "BIM up-regulation was already shown to be mediated by STAT1 in IL-21-treated lymphocytic leukaemia cells and TNF-α+IFN-γ-exposed β-cells, while CHOP activity is required for BIM up-regulation and apoptosis induction in thapsigargin-treated thymocytes and growth factor-deprived lymphoid precursors." (PMID 22347430, 2012).
malignant meningiomas (1 paper, 2022). "Our proteomic results showed that compared with that in meningothelial meningiomas, the expression of STAT1 was increased in malignant meningiomas." (PMID 36203966, 2022). "Meanwhile, we will clarify whether the PP2A inhibitor LB-100 upregulates the expression of B7-H3 by increasing the phosphorylation of STAT1, which may increase the sensitivity of malignant meningiomas to B7-H3-targeted immunotherapy." (PMID 36203966, 2022).
megakaryoblastic leukemia (1 paper, 2022). "The myocardin-related transcription factor megakaryoblastic leukemia (MKL) induces the expression of the signal transducer and activator of transcription 1 (STAT1) via its SAP-domain (SAF-A/B, acinus and PIAS protein domain) activity, which upregulates PFN expression." (PMID 36428995, 2022).
mesangial sclerosis (1 paper, 2020). "While Sox2Cre::Pdgfrb+/K::Stat1+/− mice die at 3 weeks of age, 9‐week‐old Sox2Cre::Pdgfrb+/K::Stat1−/− mice closely resembled the phenotype of Foxd1Cre::Pdgfrb+/J mice, with mesangioproliferative glomerulonephritis, mesangial sclerosis, and interstitial fibrosis (Fig EV4)." (PMID 31943786, 2020).
metastasis (1 paper, 2018). The spread or migration of cancer cells from one part of the body (where they first appeared) to another. "Association of the expression of MDM2, IGF1, STAT1, and RAC1 and clinical characteristics such as age, gender, Campanicci grade, pathological fracture, and lung metastasis was also analyzed using the Kendall's tau-b test." (PMID 29651441, 2018).
microphthalmia (1 paper, 2024). Congenital or developmental anomaly in which the eyeballs are abnormally small. "Further upstream of the caspases in the apoptosis pathway, XAF1 (LFC +5.26, p < 0.0001), IRF1 (LFC +1.53, p < 0.000341), and STAT1 (LFC +1.850, p < 0.000000118) and pro-apoptotic genes BIRC3 (LFC +2.39, p < 0.00000695) and BIK (LFC +1.43, p < 0.00178) was upregulated in microphthalmia patients." (PMID 38821055, 2024).
middle ear disease (1 paper, 2022). "In comparison, we observed only slight auditory function decline in mock infected Stat1-KO mice, which may reflect mild middle ear disease." (PMID 35605008, 2022).
middle ear infection (1 paper, 2022). "At the onset of hearing loss at 3 w.p.i., our Stat1-KO mice were around the susceptible age for developing middle ear infections." (PMID 35605008, 2022). "The Stat1-KO mice are known to develop middle ear infection spontaneously around 12–13 weeks of age resulting in unilateral or bilateral conductive hearing loss, which resolves in several weeks." (PMID 35605008, 2022). "There is a clear difference to the reported spontaneous middle ear infection in Stat1-KO mice with no apparent pathology in the cochlea." (PMID 35605008, 2022).
migraine (1 paper, 2024). "Among the pathways, STAT1-, PEA3- and retinol metabolism-related sets implicate immunologic and vitamin A-bound processes behind migraine." (PMID 39333847, 2024).
monocytic leukemia (1 paper, 2017). "Previous reports demonstrated that IL-17A activated both STAT1 and STAT3 in human monocytic leukemia cells and keratinocytes and human keratinocytes, implying that IL-17A can induce M1 and M2 macrophage-related proteins via direct activation of both STAT1 and STAT3 in the skin of mouse." (PMID 28963556, 2017).
mucinous tumors (1 paper, 2018). "High level of STAT1 was found in ovarian serous malignant tumors rather than in mucinous tumors, indicating that it is a tissue biomarker at least and is tumor-type specific." (PMID 29751820, 2018).
mucormycosis (1 paper, 2015). "While IFN-γ/STAT1 signaling was similar between groups, naïve T cells from patients with IA, but not those with mucormycosis, exhibited reduced responsiveness to IL-6 as measured by STAT3 phosphorylation." (PMID 25835547, 2015).
Mycobacterium avium complex (1 paper, 2025). "Notably, despite MSMD patients’ susceptibility to Mycobacterium avium complex (MAC) infections (except tuberculosis mycobacterial infections), Mycobacterium marinum has not been previously reported in MSMD or STAT1 LOF patients." (PMID 40491431, 2025).
myositis (1 paper, 2014). "In this study, we could identify in the myositis transcriptomes only IFNγ but not IFNα as a predominant trigger for PSMB8/-9, which also correlated with the expression of STAT1 and IRF-1." (PMID 25098831, 2014).
myxoma (1 paper, 2024). A benign soft tissue neoplasm characterized by the presence of spindle and stellate cells, lobulated growth pattern, and myxoid stroma formation. "The secretion of IL-6 from the myxoma cells was significantly inhibited by the treatment with AG490 (JAK2 inhibitor, 100 μmol/L), piceatannol (STAT1/3 inhibitor, 100 μmol/L), LLL12 (STAT3 inhibitor, 10 μmol/L), and Ly294002 (PI3K/Akt inhibitor, 30 μmol/L)." (PMID 38396907, 2024).
Netherton syndrome (1 paper, 2023). Netherton syndrome (NS) is a skin disorder characterized by congenital ichthyosiform erythroderma (CIE), a distinctive hair shaft defect (trichorrhexis invaginata; TI) and atopic manifestations. "Cutaneous viral infections are described in CARD11, LCK, NEMO, GATA2, STK4, DOCK8, and STAT2 deficiencies, STAT1 GOF, Netherton syndrome, WHIM syndrome, and WILD (warts, depressed cell‐mediated immunity, primary lymphedema, and anogenital dysplasia) syndrome." (PMID 37102642, 2023).
neuropathy (1 paper, 2015). A disorder affecting the nervous system that manifests with pain, tingling, numbness, and/or muscle weakness.
ocular hypertensive (1 paper, 2021). "The mRNA expression of STAT1, STAT2, and STAT3 was increased significantly in the retina of ocular hypertensive animals." (PMID 33628191, 2021). "To shed more light on this idea, we measured the changes in the mRNA expression of transcription factors STAT1, STAT2, and STAT3 and found that mRNA levels of all STATs were increased in the retina of ocular hypertensive animals." (PMID 33628191, 2021). "Interestingly, up-regulation of STAT1, STAT2, and STAT3 mRNA was blocked in SNC-121 treated ocular hypertensive animals." (PMID 33628191, 2021).
Oral ulcer (1 paper, 2025). Erosion of the mucous mebrane of the mouth with local excavation of the surface, resulting from the sloughing of inflammatory necrotic tissue. "Patients with mutations associated with high inflammatory state such as STAT1 gain-of-function, RAS-associated mutations and A20 haploinsufficiency present with oral ulcers." (PMID 40465409, 2025).
oropharyngeal cancers (1 paper, 2013). Carcinoma, predominantly squamous cell, arising from the epithelial cells of the oropharynx.
oropharyngeal squamous cell carcinomas (1 paper, 2013).
oropharyngeal tumors (1 paper, 2013). "In immunohistochemical study, nuclear STAT1 expression was slightly higher in HPV-positive compared to HPV-negative oropharyngeal tumors (P=0.18); however, cytoplasmic STAT1 was significantly lower in HPV-positive cases (P=0.03)." (PMID 23708675, 2013).
osteonecrosis (1 paper, 2024). A none disease characterized by death of bone tissue due to a lack of blood supply. "EP300, TRAF6, STAT1, JAK1, CASP8, and JAK2 have exhibited significant differences in SANFH (spontaneous osteonecrosis of the femoral head)." (PMID 38204239, 2024). "In conclusion, EP300, TRAF6, STAT1, JAK1, CASP8, and JAK2 exhibit significant differences in SANFH (spontaneous osteonecrosis of the femoral head)." (PMID 38204239, 2024).
otitis media (1 paper, 2020). Inflammation of the anatomical structures of the middle ear, which is most often caused by an infectious process. "The STAT1-KO mice seem to be susceptible to otitis media, but we cannot exclude that other factors contribute to inflammation in mice, as the otitis media is a multifactorial disease." (PMID 32991625, 2020). "This suggests that loss of STAT1 predispose the mice to spontaneous otitis media." (PMID 32991625, 2020). "Thus, the study supports the new role of STAT1 as otitis media predisposition gene." (PMID 32991625, 2020). "We report that mice with ablation of the STAT1 gene regularly develop otitis media without any experimental interventions and even though those mice were housed in pathogen-free conditions." (PMID 32991625, 2020). "STAT1-KO mice do not show any obvious structural deformations, but presented increased ABR thresholds suggesting that otitis media could be the major cause of hearing impairment." (PMID 32991625, 2020).
penile cancer (1 paper, 2024). A primary or metastatic malignant neoplasm that affects the penis. "During tumorigenesis phase of penile cancer, the expression evolution of JAK-STAT-SOCS1 axis was characterized by the upregulation of JAK2, STAT1, STAT2, STAT3 and STAT4." (PMID 38774752, 2024).
Pleuritis (1 paper, 2010). Inflammation of the pleura. "From day 15–24, a fibrinous peritonitis, pleuritis and pyogranulomatous lesions in spleen, liver and omentum developed as the major lesions that likely contributed to illness and death in the STAT1−/− mice." (PMID 20386712, 2010).
Pneumocystis infection (1 paper, 2018). "In our murine model of Pneumocystis infection, PCR results from lung tissue showed upregulated expressions of STAT3 and STAT5 and similar levels of STAT1 expression in IL-9−/− mice compared with WT mice." (PMID 29887863, 2018).